APOB (apolipoprotein B)
Diseases named in the same sentence as APOB in open-access papers (continued):
Sharing a sentence is not in itself a finding about the gene and the disease.
diabetes (continued). "In accordance, the 2019 guidelines update have also highlighted the importance of ApoB and non-HDL-c determination in patients with diabetes." (PMID 32505210, 2020). "The sdLDL-C levels and prevalance of the hyper-apoB/-TG group were not different between patients with CAD with and without diabetes (data not shown)." (PMID 28125987, 2017). "LDL-C, non-HDL-C, and apoB levels were higher in patients with CAD than those in healthy subjects and were further elevated in patients with diabetes." (PMID 28125987, 2017). "Recent observational studies showed that the ApoB/ApoA1 ratio can predict the progression of non-major coronary artery lesions and the occurrence of MACE in patients with diabetes complicated with acute coronary syndrome after percutaneous coronary intervention." (PMID 38310324, 2024). "ApoB, Ox-LDL and 4-HNE were present in all placentae, regardless of diabetes status." (PMID 33504507, 2021). "Our study found a significant negative association between early kidney dysfunction, i.e., pre-CKD condition with G1 and G2 categories of eGFR mitigation and Apolipoprotein B Kazakh hypertensives without comorbidities such as CVD, diabetes, CKD, acute kidney conditions, and nephrotic syndrome." (PMID 34066182, 2021). "Therefore, we recommend that more attention should be paid when TG and apoB (or non-HDL-C) levels are high, particularly for patients with diabetes and those with CAD, because their sdLDL-C levels are likely to be substantially elevated." (PMID 28125987, 2017). "Furthermore, ApoB may be used instead of non-HDL-C for individuals with high TG, diabetes, obesity, or very low LDL-C levels." (PMID 37892070, 2023). "To determine whether extravasated LDL that has undergone oxidation is present in human placental tissue, we performed immunohistochemistry to detect ApoB, Ox-LDL and 4-HNE in a small number of placental sections from women with either pregestational type 1 diabetes (n=3) or without diabetes (n=4)." (PMID 33504507, 2021). "Individuals with diabetes often have high levels of atherogenic lipoproteins and cholesterol reflected by elevated low-density lipoprotein cholesterol (LDL-C), non-high-density lipoprotein cholesterol (non-HDL-C), apolipoprotein B (ApoB), and LDL particle number (LDL-PN)." (PMID 31706300, 2019). "As it actually estimates the level of all apoB-carrying lipoproteins, non-HDL-C may represent a simple and inexpensive surrogate to apoB measurement, especially in selected patients groups, such as hypertriglyceridemic patients and/or patients with diabetes." (PMID 21356116, 2011). "Thus, in addition to LDL-C, triglyceride, HDL-C, non-HDL-C, total apolipoprotein (apo) B, apoB/A-I, and TC/HDL-C levels are considered significant predictors of cardiovascular events and have been validated in large prospective studies in cardiovascular and diabetes epidemiology." (PMID 31443489, 2019). "However, in specific patient populations—those with elevated triglyceride (TG), diabetes mellitus (DM), obesity, or very low LDL-C concentrations—the assessment of non-high-density lipoprotein cholesterol (non-HDL-C) or apolipoprotein B (apoB) levels is recommended." (PMID 41517276, 2025).
Hypercholesterolemia (347 papers, 2005 to 2026). An increased concentration of cholesterol in the blood. "Apolipoprotein B (APOB) is a key structural component of atherogenic lipoproteins and one of the principal genes implicated in familial hypercholesterolemia (FH)." (PMID 41590863, 2026). "The patient also presented with two homozygous missense variants, VUS—p.Ala10Val and p.Gly753Glu—in the APOB gene, which are associated with hypobetalipoproteinemia and familial hypercholesterolemia." (PMID 40870862, 2025). "Among patients with heterozygous familial hypercholesterolemia, nuclear factor-kappa B (NF-kB) activity of monocytes in blood was independently associated with apolipoprotein B (r = 0.287, P = 0.03) and oxidized LDL (r = 0.300, P = 0.02)." (PMID 40166678, 2025). "Hypobetalipoproteinemia, hypercholesterolemia and normotriglyceridemic hypobetalipoproteinemia are caused by mutations in the APOB or its regulatory region." (PMID 39295604, 2024). "Both APOB R3500Q and R3500W variants are also implicated in familial hypercholesterolemia (FH), accounting for 12% of FH cases." (PMID 38393015, 2024). "In mothers with hypercholesterolemia, higher maternal TC, TG, and apoB levels were associated with a larger increase in offspring body weight up to 8 years of age (0.01 ≤ Pinteraction ≤ 0.04)." (PMID 36747215, 2023). "Mipomersen decreased apoB levels by 36% in patients with severe hypercholesterolemia and in patients with increased CVD risk." (PMID 37908502, 2023). "Familial hypercholesterolemia (FH) due to a founder variant in Apolipoprotein B (ApoBR3500Q) is reported in 12% of the Pennsylvania Amish community." (PMID 35300601, 2022). "Here we report an extremely rare family where phenotypes of familial hypercholesterolemia (FH) are canceled by coexistence of FHBL1 caused by an truncating mutation in apolipoprotein B (APOB)." (PMID 36003908, 2022). "The familial hypercholesterolemia causing APOB variant rs5742904_R3527Q15,43 which is enriched in the Amish provides an extreme example." (PMID 35393526, 2022). "The second is the well-established Amish-enriched familial hypercholesterolemia (FH) causing variant R3527Q (rs5742904) in the APOB gene (MAF = 0.06 vs 0.0004) that was previously linked to LDL and TC by our group and others." (PMID 35393526, 2022). "The second ASO drug, Mipomersen was for homozygous familial hypercholesterolemia (HoFH), which forms a double-strand complex with apolipoprotein B (APOB) transcript and causes its degradation through ribonuclease RNase H." (PMID 35052837, 2022).
Hypercholesterolemia (continued). "In this case-control study, rs693 (in exon 26 of APOB) and rs515135 (5 'end of APOB) singlenucleotide polymorphisms (SNPs) were analyzed in 120 cases of familial hypercholesterolemia and 120 controls." (PMID 30507093, 2019). "In four index patients and one positive screened sibling results for familial hypercholesterolemia showed a disease causing genetic mutation either on LDL-R or on ApoB." (PMID 31238984, 2019). "We identified a set of Mendelian variants that co-occur in individuals with BD more frequently than their unaffected family members, including the R3527Q mutation in APOB associated with hypercholesterolemia." (PMID 30315151, 2018). "A few other mutations leading to hypercholesterolemia were described in the following years and were all located in a specific region of the APOB gene." (PMID 29386597, 2018). "For example, we removed 55 individuals carrying the APOB R3527Q variant for familial hypercholesterolemia and tested for an association between BD and LDL risk score in the remaining set of 339 individuals (β = 0.43, p = 0.0006)." (PMID 30315151, 2018). "While truncation mutations in the APOB gene cause hypobetalipoproteinemia, mutations causing hypercholesterolaemia are due to missense mutations that result in ligand-defective apoB protein." (PMID 28405938, 2017). "Variants in the APOB gene have been associated with hypercholesterolemia, hypobetalipoproteinemia, apolipoprotein B deficiency, hypertriglyceridemia, and ischemic stroke." (PMID 26636822, 2015). "The heterozygous APOB variant seen in pacemaker patient 7, p.R3527Q, has been previously seen in heterozygosity in individuals with hypercholesterolemia, MI, and ischemic heart disease (summarized in OMIM 107730)." (PMID 26636822, 2015). "Familial defective ApoB hypercholesterolemia is a result of non-sense or frame-shift mutations within the LDL-receptor binding domain of ApoB and causes severe hypercholesterolemia and premature cardiovascular disease." (PMID 22989709, 2012). "Several investigators have also associated some genetic variations of apolipoprotein-B with the development of hypercholesterolemia and CHD." (PMID 18377643, 2008). "Abnormalities in the apoB metabolism are responsible for the generation of hypercholesterolemia and increased risk of coronary heart disease." (PMID 16271152, 2005). "So the present study demonstrates that Se deficiency leads to up regulation of apoB expression during experimental hypercholesterolemia." (PMID 16271152, 2005). "Subsequently identified as the third pathogenic gene associated with familial hypercholesterolemia, along with low-density lipoprotein receptors (LDLRs) and apolipoprotein B (ApoB) genes, PCSK9 has been extensively studied concerning its interplay with lipid homeostasis." (PMID 39139638, 2024). "Our aim was to identify and characterize APOB variants in patients with hypercholesterolemia." (PMID 37108800, 2023).
Hypercholesterolemia (continued). "A similar strategy has been used clinically to treat homozygous hypercholesterolemia using Mipomersen and Inclisiran, which are RNase H1-active ASOs that induce the degradation of mRNAs encoding apolipoprotein B and proprotein convertase subtilisin–kexin type 9 (PCSK9), respectively." (PMID 36737429, 2023). "Familial hypercholesterolemia (FH) is a rare autosomal dominant genetic disorder caused by defective low-density lipoprotein (LDL) receptors or abnormal apolipoprotein B. FH raises the risk of premature atherosclerotic disease and cardiovascular death in young adults." (PMID 37477701, 2023). "Mutations in APOB are the second most frequent cause of familial hypercholesterolemia (FH)." (PMID 37108800, 2023). "Mutation in the gene for APOB will lead to hypercholesterolemia." (PMID 35586687, 2022). "The use of multi-gene panels or whole-exome/genome sequencing as first line of genetic diseases diagnosis will bring out an increasing number of exonic and intronic APOB variants of uncertain significance in patients with either hypobetalipoproteinemia or hypercholesterolemia." (PMID 35457099, 2022). "PAVs in the hypercholesterolemia-associated APOE gene were associated with apoB (p=3.5×10−4), total HDLC (p=8.0×10−4), and total cholesterol and cholesterol esters in LDL particles, with large negative effects observed for the previously reported rare p.Glu57Lys (rs201672011) variant." (PMID 36419110, 2022). "Furthermore, the intake of saturated fatty acids (SFAs) was positively associated with serum total cholesterol (TC), LDL-C and Apolipoprotein B (ApoB) levels in Familial Hypercholesterolemia (FH) affected children." (PMID 35405957, 2022). "However, many studies have focused on investigating an association of APOB variants with metabolic diseases such as familial hypercholesterolemia." (PMID 35999587, 2022). "Apolipoprotein B (ApoB) is an amphipathic glycoprotein that plays a central role in human lipoprotein metabolism, the mutation of which could either cause hypercholesterolemia or hypobetalipoproteinemia." (PMID 34938739, 2021). "Familial defect in apolipoprotein B-100 is associated with moderate to severe hypercholesterolemia." (PMID 32000699, 2020). "Mutations in ApoB gene can cause familial hypercholesterolemia." (PMID 28086795, 2017). "Furthermore, ezetimibe add-on therapy significantly reduced the ratio of apoB to apoA-I in high-risk patients with hypercholesterolemia (p < 0.01)." (PMID 19821987, 2009).
Hypercholesterolemia (continued). "Pathogenic variants in APOB can impair the normal clearance or metabolism of LDL particles, resulting in elevated cholesterol levels and hypercholesterolemia." (PMID 41189009, 2025). "Gain-of-function mutations in PCSK9 are linked to elevated plasma LDL cholesterol levels and constitute a third genetic cause of familial hypercholesterolemia, alongside mutations affecting the LDL receptor and apolipoprotein B (apoB)." (PMID 40593368, 2025). "In the STELLAR clinical trial, rosuvastatin at doses ranging from 10 mg to 40 mg was reported to be superior compared to other statins in improving the lipid profile in subjects with hypercholesterolemia, including ApoB levels." (PMID 38393015, 2024). "Mipomersen, administered subcutaneously in three phase III trials conducted in patients with moderate to severe hypercholesterolemia, demonstrated its efficacy in reducing levels of apoB, LDL-C, triglycerides, and Lp (a) when compared with a placebo." (PMID 39685877, 2024). "Our results highlight that hypercholesterolemia is a neglected cardiovascular risk factor in Portugal, with more than 50% of the population with TC, LDL-C, or apoB above the recommended values for low and moderate risk." (PMID 39598108, 2024). "It has been shown that heterozygous mice for a knockout in ApoB are protected against diet-induced hypercholesterolemia after being fed a diet rich in fat and cholesterol." (PMID 38419006, 2024). "Our results highlight that hypercholesterolemia is a neglected cardiovascular risk factor with over half of the population with TC, LDL-C, and apoB above recommended values." (PMID 39598108, 2024). "The distribution of APOB-Xba I showed that the hypercholesterolemia group had a higher frequency of the TT genotype compared to the normocholesterolemia group (15% vs. 2.5%), and the difference was statistically significant (OR=6.8, p=0.047)." (PMID 39469407, 2024). "Lifestyle interventions have been shown to decrease circulating apoB and increase circulating apoA1 in children with obesity and hypercholesterolemia." (PMID 38127151, 2024). "Fish fed HCD developed hypercholesterolemia as indicated by significantly elevated ApoB-containing lipoproteins (ApoB-LPs) and increased plasma levels of cholesterol and cholesterol esters." (PMID 39218217, 2024). "Familial hypercholesterolemia is caused primarily by mutations in the gene encoding the LDL receptor (LDL-R), with less frequent mutations in the apolipoprotein B (APOB) and proprotein convertase subtilisin/kexin type 9 (PCSK9) genes." (PMID 39350832, 2024). "Mipomersen, an antisense oligodeoxynucleotide inhibitor of apolipoprotein B-100, has been approved for the treatment of familial hypercholesterolemia." (PMID 38390206, 2024). "Mutations in genes related to the LDL receptor (LDL-R), apolipoprotein B (APOB), and proprotein convertase subtilisin/kexin type 9 (PCSK9) are the main molecular mechanisms causing familial hypercholesterolemia." (PMID 39350832, 2024).